KCNN1 (potassium calcium-activated channel subfamily N member 1)
Description:
Small conductance calcium-activated potassium channel that mediates the voltage-independent transmembrane transfer of potassium across the cell membrane through a constitutive interaction with calmodulin which binds the intracellular calcium allowing its opening. The current is characterized by a voltage-independent activation, an intracellular calcium concentration increase-dependent activation and a single-channel conductance of about 3 picosiemens. Also presents an inwardly rectifying current, thus reducing its already small outward conductance of potassium ions, which is particularly the case when the membrane potential displays positive values, above + 20 mV (Probable). Activation is followed by membrane hyperpolarization (By similarity). Thought to regulate neuronal excitability by contributing to the slow component of synaptic afterhyperpolarization (By similarity).
Synonyms: SK1; SKCa1; hSK1; KCa2.1
Tractability: Small molecule: a high-quality ligand is known; it belongs to a druggable protein family. Antibody: its Gene Ontology location is reachable by antibodies, with high confidence; UniProt predicts a signal peptide or a membrane-spanning region. PROTAC: ubiquitination databases record sites on it; a small molecule that binds it is known.
Target class: Voltage-gated ion channel; Ion channel; Calcium-activated potassium channel; Potassium channels
Safety:
Unwanted effects reported when the protein is acted on. In parentheses: how it was acted on, where the effect was seen, and who reports it.
ataxia (activation, acute dosing; central nervous system, cardiovascular; source: Lynch et al. (2017))
convulsions (inhibition, acute dosing; central nervous system, cardiovascular; source: Lynch et al. (2017))
decreased convulsions (activation, acute dosing; central nervous system, cardiovascular; source: Lynch et al. (2017))
decreased locomotor activity (activation, acute dosing; central nervous system, cardiovascular; source: Lynch et al. (2017))
increased atrial refractory period (inhibition, acute dosing; central nervous system, cardiovascular; source: Lynch et al. (2017))
neurotoxicity (inhibition, acute dosing; central nervous system, cardiovascular; source: Lynch et al. (2017))
Gene: Protein-coding gene on chromosome 19 (17,947,484 to 18,000,085, forward strand). Ensembl gene ENSG00000105642.
Subcellular location: Membrane; Cytoplasm, myofibril, sarcomere, Z line
Subcellular location (Human Protein Atlas): Actin filaments; Cytosol
Pathways (Reactome):
Neuronal System: Ca2+ activated K+ channels
Gene Ontology:
Molecular function: inward rectifier potassium channel activity; small conductance calcium-activated potassium channel activity; calcium-activated potassium channel activity; calmodulin binding
Biological process: potassium ion transmembrane transport; chemical synaptic transmission; potassium ion transport
Cellular component: neuron projection; neuronal cell body; plasma membrane; voltage-gated potassium channel complex; membrane; synapse; Z disc
Genetic constraint (gnomAD): Loss-of-function variants: 19 observed, 42.39 expected, observed/expected ratio (o/e) 0.45, 90% interval 0.31 to 0.66. The upper end of that interval is the gene's LOEUF score, 0.66, which puts it in group 2 of 6, group 1 being the genes least tolerant of losing a copy. Missense variants: 631 observed, 747.09 expected, observed/expected ratio (o/e) 0.84, 90% interval 0.79 to 0.9. Synonymous variants: 324 observed, 319.98 expected, observed/expected ratio (o/e) 1.01, 90% interval 0.92 to 1.11.
Homologues: Orthologues: chimpanzee KCNN1 (100% identical), macaque KCNN1 (99% identical), pig KCNN1 (93% identical), guinea pig KCNN1 (86% identical), mouse Kcnn1 (83% identical), dog KCNN1 (79% identical), rat Kcnn1 (78% identical), zebrafish kcnn1a (73% identical), tropical clawed frog kcnn1 (72% identical), Drosophila melanogaster SK (55% identical), Caenorhabditis elegans kcnl-2 (41% identical), Caenorhabditis elegans kcnl-1 (35% identical), and 3 more. Paralogues in human: KCNN2 (69% identical), KCNN3 (67% identical), KCNN4 (35% identical).
Diseases named in the same sentence as KCNN1 in open-access papers:
KCNN1 is named in the same sentence as 22 diseases in open-access papers, as found by Europe PMC text mining. Sharing a sentence is not in itself a finding about the gene and the disease. The quoted sentences say what the papers report.
atrial fibrillation (4 papers, 2018 to 2025). A disorder characterized by an electrocardiographic finding of a supraventricular arrhythmia characterized by the replacement of consistent P waves by rapid oscillations or fibrillatory waves that vary in size, shape and timing and are accompanied by an irregular ventricular response. "KCNN1 is also involved in the electrical remodeling of the heart during chronic atrial fibrillation." (PMID 30587240, 2018). "Atrial KCNN1 channels are remodeled in patients and pigs with atrial fibrillation." (PMID 34111326, 2021). "The small conductance calcium activated potassium channel (KCNN1-3; KCa2.1–3) is recognized as a possible new anti-arrhythmic drug target for treatment of atrial fibrillation (AF)." (PMID 40476174, 2025).
alcohol dependence (2 papers, 2015 to 2021). Physical and psychological dependence on alcohol. "Variants in the human orthologue of Serinc2 and Kcnn1 are strongly implicated in alcohol dependence." (PMID 34573345, 2021).
bone tumor (1 paper, 2024). "Unexpectedly, we detected Kcnn1 (potassium intermediate/small conductance calcium-activated channel, subfamily N, member 1), which is mainly expressed in the brain but also associated with the bone tumor Ewing sarcoma." (PMID 39261515, 2024).
COVID-19 (1 paper, 2024). A disease caused by infection with severe acute respiratory syndrome coronavirus 2. "Given that AAV has been used as a delivery vehicle in the COVID-19 vaccine, the local delivery of exogenous KCNN1 via AAV into the DRGs may hold potential as a novel antinociceptive treatment for managing neuropathic pain." (PMID 38912580, 2024).
diabetic neuropathy (1 paper, 2022). A chronic, pathological complication associated with diabetes mellitus, where nerve damages are incurred due to diabetic microvascular injury involving small blood vessels that supply these nerves, resulting in peripheral and/or autonomic nerve dysfunction. "Five of them, KCNA2, KCNA4, KCNQ5, KCNN1 and KCNS1, were also negative for screening in a diabetic neuropathy population." (PMID 36430572, 2022).
dilatative cardiomyopathy (1 paper, 2021). "Differences in pathophysiology between the porcine model with a tachymyopathy phenotype and humans with severe ischemic or dilatative cardiomyopathy may account for differential KCNN1 remodeling observed here." (PMID 34111326, 2021).
Ewing sarcoma (1 paper, 2022). A small round cell tumor that lacks morphologic, immunohistochemical, and electron microscopic evidence of neuroectodermal differentiation. "The main oncogene in Ewing sarcoma directly drives a high expression of a previously unknown variant KCNN1 (encoding the KCa2.1 channel) that we also verified in samples from >200 patients." (PMID 36230742, 2022).
morbid obesity (1 paper, 2017). An excess of body weight, normally defined as an individual with a body mass index greater than 35 or a body weight greater than one hundred percent of ideal body weight. "(I) KCNN1: The lipotoxicity in morbid obesity can gradually impair insulin action in the liver and muscle, aggravating insulin resistance, and Ye, J proposed an energy-based concept of insulin resistance, in which insulin resistance is a result of energy surplus in cells." (PMID 29132311, 2017).
osteosarcoma (1 paper, 2022). A usually aggressive malignant bone-forming mesenchymal neoplasm, predominantly affecting adolescents and young adults. "We found that osteosarcoma cell lines have negligible KCNN1 expression compared to EwS cell lines (expression relative to GAPDH and YWHAZ: EwS: 0.02 ± 0.003, N = 3, n = 48; OS: 0.0001 ± 0.00002, N = 3, n = 22)." (PMID 36230742, 2022). "Overall, these findings indicate that KCNN1 has a considerable tissue specificity in EwS compared to osteosarcoma and healthy bone tissue." (PMID 36230742, 2022).
peripheral nerve injury (1 paper, 2024). Injury to a peripheral nerve. "Peripheral nerve injury-induced KCNN1 downregulation contributes to neuropathic pain via decreased action potential afterhyperpolarization and total Kv currents and increased excitability in the injured neurons of dorsal root ganglion." (PMID 38912580, 2024). "Peripheral nerve injury downregulates Kcnn1 mRNA and KCNN1 protein in the injured DRG." (PMID 38912580, 2024).
tumor (2 papers, 2017 to 2022). "This raises the question of whether the KCNN1 mRNA is translated into KCa2.1 protein in EwS tumor cells at all." (PMID 36230742, 2022). "GABA receptor signaling pathway enrichment was defined by elevated expression of GABRB3 and potassium channel genes, KCNN1, KCNN2, and KCNQ3, and decreased expression of ADCY2, which have all been indicated as important in tumor growth (32, –, 34)." (PMID 28049147, 2017). "Throughout our study, we were confronted with the discrepancy that high KCNN1 expression at the mRNA level in all the EwS lines studied as well as tumor cells in EwS patient material is by no means reflected in the functional assays and in the clinical data." (PMID 36230742, 2022). "Furthermore, we found out that KCNN1 is expressed in tumor cells but not in the surrounding healthy bone tissue using RNA in situ hybridization (RNAish) (N = three whole EwS tissue slides)." (PMID 36230742, 2022).
KCNN1 also shares sentences with these, for which no sentence is quoted: alcoholism (1 paper); bone sarcoma (1); breast carcinoma (1); cancer (1); cardiac disease (1); cardiovascular disease (1); depression (1); heart failure (1); Insulin resistance (1); neurodegenerative disease (1); spinocerebellar ataxia 3 (1).